BACE1 (beta-secretase 1)
Diseases named in the same sentence as BACE1 in open-access papers (continued):
Sharing a sentence is not in itself a finding about the gene and the disease.
Alzheimer disease (continued). "Recently, Sema3A-mediated growth cone collapse has been suggested to have connection with a major drug target of Alzheimer's disease: BACE1 (beta-site amyloid precursor protein-cleaving enzyme 1)." (PMID 31097955, 2019). "In the brain, BACE1 is an aspartyl protease that contributes to the pathogenesis of Alzheimer’s disease." (PMID 31816964, 2019). "The glycosaminoglycan heparin, widely used as a clinical anticoagulant, has previously been shown to inhibit the Alzheimer’s disease-relevant β-secretase 1 (BACE1)." (PMID 31100859, 2019). "Inhibition of BACE1 is a putative therapy for Alzheimer's disease, and RTN3A1 indirectly inhibits BACE1 activity by two mechanisms." (PMID 30802174, 2019). "Previous studies have demonstrated that Sp1 overexpression upregulates APP and BACE1 expression, which is involved in Alzheimer's disease." (PMID 31049134, 2019). "Recent evidence has indicated that beta-secretase 1 (BACE1) is involved in the production of amyloid beta (Aβ) in patients affected with Alzheimer’s disease (AD)." (PMID 31558988, 2019). "Excess Aβ production by the key protease BACE1, results in Aβ aggregation, forming amyloid plaques, all of which contribute to the pathogenesis of Alzheimer’s disease." (PMID 30842555, 2019). "BACE1 is a prime therapeutic target for lowering cerebral Aβ concentrations in Alzheimer’s disease and the clinical development of BACE1 inhibitors is being intensely investigated." (PMID 31108937, 2019). "We extracted 15 pterosin derivatives from Pteridium aquilinum that inhibited β-site amyloid precursor protein cleaving enzyme 1 (BACE1) and cholinesterases involved in the pathogenesis of Alzheimer’s disease (AD)." (PMID 30755593, 2019). "The most active compounds from each series were, in turn, evaluated against the following enzyme targets involved in Alzheimer’s disease, β-secretase (BACE-1) and lipoxygenase-15 (LOX-15), as well as for anti-oxidant potential." (PMID 31683761, 2019). "In November 2017, Merck reported slight reduction of β-amyloid burden below baseline by 2–4% after 18 months long treatment of mild-to-moderate AD patients with the BACE1 inhibitor verubecestat (Clinical Trials on Alzheimer’s Disease conference)." (PMID 29327084, 2018). "β-Site APP-cleaving enzyme 1 (BACE1) inhibition is considered one of the most promising therapeutic strategies for Alzheimer’s disease, but current BACE1 inhibitors also block BACE2." (PMID 30456346, 2018). "Further study indicated that berberine acted as a high-affinity BACE1 inhibitor and prevented Aβ1-42 aggregation to delay the pathological process of Alzheimer’s disease." (PMID 30087614, 2018). "Taken together, our results support the repurposing of BACE1 inhibitors, currently in clinical trials for Alzheimer’s disease, to recover some active IR in the liver of patients with diabetes, thus reducing hepatic insulin resistance." (PMID 29610518, 2018). "BACE1 not only holds clinical relevance in the pathogenesis of Alzheimer’s disease, but also has been a molecular target for drug development." (PMID 29300757, 2018). "For example, Albany Molecular Research Inc. reported on their development of an experimental drug for the treatment of Alzheimer's disease called verubecestat (MK-8931), which is an inhibitor of BACE1." (PMID 30050590, 2018). "The donepezil analogues 8c, 8e, 8f, and 8l also displayed potent BACE1 inhibitory activities, and thus appeared to be multifunctional compounds for the treatment of Alzheimer’s disease." (PMID 30544832, 2018). "The design of novel inhibitors to target BACE1 with reduced cytotoxicity effects is a promising approach to treat Alzheimer's disease (AD)." (PMID 29910719, 2018). "The β-site APP cleaving enzyme 1 (BACE1) is among the most significant targets for novel drugs to treat Alzheimer's disease (AD)." (PMID 29910719, 2018).
Alzheimer disease (continued). "Beta-site amyloid-precursor-protein cleaving enzyme 1 (BACE1) is considered as a potential drug target for therapeutic intervention in Alzheimer’s disease (AD) for years." (PMID 30093858, 2018). "The beta‐site amyloid precursor protein cleaving enzyme‐1 (BACE‐1) initiates the generation of amyloid‐β (Aβ), and the amyloid cascade leading to amyloid plaque deposition, neurodegeneration, and dementia in Alzheimer's disease (AD)." (PMID 30224383, 2018). "We show here that miR-19b-3p targets MID1, a protein that we have previously shown to induce protein expression of two mRNAs that are crucial for the development of amyloid plaques in Alzheimer’s disease, namely BACE1 and APP." (PMID 29293623, 2018). "β-site amyloid precursor protein cleaving enzyme 1 (BACE1) is the rate-limiting enzyme in the production of amyloid beta (Aβ), the toxic peptide that accumulates in the brains of Alzheimer’s disease (AD) patients." (PMID 29391027, 2018). "The human β-site amyloid cleaving enzyme (BACE1) has been considered as an effective drug target for treatment of Alzheimer’s disease (AD)." (PMID 29538306, 2018). "The critical role of BACE-1 in the formation of neurotoxic ß-amyloid peptides in the brain makes it an attractive target for an efficacious treatment of Alzheimer’s disease." (PMID 28505196, 2017). "Two well-documented examples of RNA masking focus on the bi-directionally transcribed genes BACE1 and HIF1α, both highly relevant to human disease, BACE1 in Alzheimer’s disease and HIF1α in cancer." (PMID 29209299, 2017). "Previous studies reported enhanced Navβ2 processing by BACE1 in Alzheimer’s disease (AD) model and patients." (PMID 29245901, 2017). "In the last decade BACE1 has emerged as an important target for experimental therapies in Alzheimer’s disease." (PMID 28334857, 2017). "The therapeutic potential of exosome-mediated siRNA delivery was demonstrated by the strong mRNA (60%) and protein (62%) knockdown of BACE1, a therapeutic target in Alzheimer's disease, in wild-type mice." (PMID 28477015, 2017). "It controls synaptic connectivity and motor coordination and is also a substrate for the β-secretase BACE1, which is highly expressed in the nervous system and an important drug target in Alzheimer's disease." (PMID 28522899, 2017). "Due to the fact that it also cleaves amyloid precursor protein, BACE1 is a therapeutic target in Alzheimer’s disease, however, consistent with its role in NRG1 processing we find that BACE1 inhibition significantly impairs myelination in our co-culture system." (PMID 28334857, 2017). "Studies have demonstrated that hypoxia induces up-regulation of beta-secretase 1 (BACE1) gene expression both in vitro and in vivo, thereby contributes to the pathology of Alzheimer's disease (AD)." (PMID 28744190, 2017). "A careful analysis of the literature data shows that there are no studies which analyzed the impact of MO extract on the expression level of BACE1 in Alzheimer's disease." (PMID 27239217, 2016). "In a brain of Alzheimer disease patients one can find an accumulation of beta-amyloid protein plaques which are formed from a peptide excised from APP protein by β (BACE1) and γ-secretases (PSEN1)." (PMID 26851889, 2016). "Results of many studies concerning the elevated level of BACE1 mRNA and protein in Alzheimer's disease provide direct and compelling reasons to develop therapies directed at BACE1 inhibition, thus reducing β-amyloid and its associated toxicities." (PMID 27239217, 2016). "The β-secretase BACE1 (β-site APP cleaving enzyme) is a key drug target in Alzheimer’s disease (AD)." (PMID 27716410, 2016). "Brain BACE1 levels increase with age, particularly in Alzheimer’s disease, and following pathological events." (PMID 27138913, 2016). "Our data reveal that neuronal BACE1 is a key regulator of metabolic homeostasis and provide a potential mechanism for the high prevalence of metabolic disturbance in Alzheimer’s disease." (PMID 27138913, 2016).
Alzheimer disease (continued). "Processing of APP by BACE1 is the rate-limiting step in the production of Aβ, and therefore, BACE1 is a major therapeutic target for the treatment of Alzheimer’s disease." (PMID 27456313, 2016). "APP mutations in the human population which increase or decrease APP processing by BACE1 can promote or protect against the development of Alzheimer’s disease, respectively." (PMID 27456313, 2016). "Beta-site amyloid precursor protein cleaving enzyme 1 (BACE1) is the enzyme involved in the abnormal production of the amyloidogenic peptide Aβ, one of the major causes of histological hallmarks of Alzheimer’s disease (AD)." (PMID 27754406, 2016). "Inhibition of β-secretase BACE1 is considered one of the most promising approaches for treating Alzheimer's disease." (PMID 27727204, 2016). "Inhibition of the protease β-site amyloid precursor protein-cleaving enzyme 1 (BACE1) is a promising treatment strategy for Alzheimer’s disease, and a number of BACE inhibitors are currently progressing through clinical trials." (PMID 27456313, 2016). "Knockout of BACE1 prevents Aβ production and improves memory in mouse models of Alzheimer’s disease." (PMID 27456313, 2016). "β-amyloid (Aβ) is produced by the β-secretase 1 (BACE1)-mediated enzymatic cleavage of the amyloid precursor protein through the amyloidogenic pathway, making BACE1 a therapeutic target against Alzheimer’s disease (AD)." (PMID 27891075, 2016). "β-Secretase 1 (BACE1) is a key enzyme in Alzheimer’s disease pathogenesis that catalyses the amyloidogenic cleavage of amyloid precursor protein (APP)." (PMID 27138913, 2016). "A major rate-limiting step for Aβ generation and deposition in Alzheimer’s disease brains is BACE1-mediated cleavage (β-cleavage) of the amyloid precursor protein (APP)." (PMID 27875558, 2016). "The β-secretase (BACE1) is responsible for the generation of amyloid-β (Aβ) fragments in the brain and is therefore proposed as a therapeutic target for Alzheimer’s disease (AD)." (PMID 26912421, 2016). "The metalloprotease meprin β cleaves the Alzheimer’s Disease (AD) relevant amyloid precursor protein (APP) as a β-secretase reminiscent of BACE-1, however, predominantly generating N-terminally truncated Aβ2-x variants." (PMID 26895626, 2016). "We hope the understanding of pH dependence of the dynamics and inhibitor binding properties of BACE-1 will aid the structure-based inhibitor design efforts against Alzheimer’s disease." (PMID 26506513, 2015). "BACE1 is an aspartyl protease that contributes to the pathogenesis of Alzheimer’s disease, and targeting BACE1 has been a long-sought-after strategy for treating Alzheimer’s disease." (PMID 26692321, 2015). "The human β-amyloid (Aβ) cleaving enzyme (BACE-1) is a target for Alzheimer’s disease (AD) treatments." (PMID 26530776, 2015). "Together, our results indicate that chemical interference of PS1/BACE1 interaction is a promising strategy for Alzheimer’s disease therapeutics." (PMID 27462420, 2015). "BACE-1 is the β-secretase responsible for the initial amyloidogenesis in Alzheimer’s disease, catalyzing hydrolytic cleavage of substrate in a pH-sensitive manner." (PMID 26506513, 2015). "The aspartic protease BACE1 is primarily expressed within the central nervous system by neurons and has been connected to the pathogenesis of Alzheimer’s disease." (PMID 25961820, 2015). "Accumulating evidence indicates that partial inhibition of β-site APP-cleaving enzyme 1 (BACE1), which initiates amyloid-β (Aβ) production, mitigates Alzheimer’s disease (AD)-like pathologies and memory deficits in a battery of transgenic mouse models." (PMID 25884928, 2015). "BACE1 initiates amyloid-β (Aβ) generation and the resultant cerebral amyloidosis, as a characteristic of Alzheimer’s disease (AD)." (PMID 26091071, 2015). "The β-site amyloid precursor protein cleaving enzyme-1 (BACE1), an essential protease for the generation of amyloid-β (Aβ) peptide, is a major drug target for Alzheimer's disease (AD)." (PMID 25592972, 2015).
Alzheimer disease (continued). "Beta-secretase 1 or β-site amyloid precursor protein cleaving enzyme 1 (BACE1) is a protease that participates in the sequential cleavage of amyloid precursor protein, a crucial enzyme in Alzheimer’s disease (AD) pathophysiology." (PMID 25654223, 2015). "β-site amyloid precursor protein (APP) cleaving enzyme 1 (BACE1) initiates the production of β-amyloid (Aβ), the major constituent of amyloid plaques in Alzheimer’s disease (AD)." (PMID 24992504, 2014). "Our characterization of Rab11 as a novel regulator of BACE1 axonal sorting in neurons, along with the identification of Rab11 as a modulator of Aβ production, raises the possibility that dysfunction of Rab11 may underlie pathogenesis in a subset of sporadic Alzheimer’s disease cases." (PMID 24386896, 2014). "These exosomes then deliver exogenously loaded Beta-secretase 1 (BACE1) siRNA, which can knock down BACE1 (Alzheimer’s disease related protein), mRNA, and protein levels in neurons, microglia and oligodendrocytes." (PMID 24463293, 2014). "The current concept for Alzheimer's disease development involves the cleavage of amyloid precursor protein (APP) to amyloid beta (Aβ) peptide by BACE1 leading to the preliminary constituent of amyloid plaques in the brains of individuals with the disease." (PMID 25254246, 2014). "BACE1 is one of the two enzymes that cleave amyloid precursor protein to generate Alzheimer's disease (AD) beta amyloid peptides." (PMID 24386896, 2014). "BACE-AS regulates the expression of β-secretase-1 (BACE1), a crucial enzyme in Alzheimer’s disease pathophysiology." (PMID 24013378, 2013). "One of the most important targets in Alzheimer disease is Beta site amyloid precursor protein cleaving enzyme-1 (BACE-1)." (PMID 24250649, 2013). "MiR-103 decreased early in Alzheimer's disease and accelerated disease progression through the regulation of BACE1 (β-site amyloid precursor protein-cleaving enzyme 1)." (PMID 24223210, 2013). "The beta amyloid (APP) cleaving enzyme (BACE1) has been a drug target for Alzheimer's Disease (AD) since 1999 with lead inhibitors now entering clinical trials." (PMID 24381583, 2013). "Previous reports, by us and others, have indicated that the levels of BACE1 protein and activity are increased in the brain cortex of patients with Alzheimer’s disease (AD)." (PMID 23613819, 2013). "β-Site amyloid precursor protein (APP) cleaving enzyme-1 (BACE1) is the β-secretase that initiates Aβ production in Alzheimer’s disease (AD)." (PMID 23820808, 2013). "The action of β-secretase (BACE1) is strongly correlated with the onset of Alzheimer’s disease (AD)." (PMID 23344193, 2012). "This work was performed as part of a project aimed at identifying strong, selective inhibitors of β-secretase (BACE-1) to overcome the shortcomings of the existing drugs to treat Alzheimer’s disease (AD)." (PMID 22701601, 2012). "The secretase BACE1 is fundamentally involved in the development of cerebral amyloid pathology in Alzheimer's disease (AD)." (PMID 22272179, 2012). "Using a COMBINE analysis, we obtained a robust COMBINE model, which should be useful for understanding the inhibitory mode of BACE-1 and in designing novel lead compounds against Alzheimer’s disease." (PMID 22925713, 2012). "In the context of Alzheimer’s disease, BACE1 and BACE2 cleavage of APP has been well characterized, and both conserved and unique cleavage sites on APP have been demonstrated for the two BACE proteins." (PMID 22797723, 2012). "BACE1 is a key enzyme for amyloid-β (Aβ) production, and an attractive therapeutic target in Alzheimer's disease (AD)." (PMID 22328928, 2012). "BACE-1, which is a crucial protease in the pathogenesis of Alzheimer's disease, is highly expressed in the brain, but it is also expressed at low levels in peripheral tissues." (PMID 22449099, 2012). "The inhibition of the activity of β-secretase (BACE-1) is a potentially important approach for the treatment of Alzheimer disease." (PMID 22925713, 2012).
Alzheimer disease (continued). "Nevertheless, our COMBINE models provided useful insights that can be used to design novel BACE-1 inhibitors for the treatment of Alzheimer’s disease." (PMID 22925713, 2012). "BACE1 provides a promising therapeutic target for Alzheimer's disease (AD) and numerous BACE1 inhibitors have been designed, of which several have gone into clinical trials." (PMID 22903875, 2012). "Attenuating Aβ production, for instance by inhibiting either of the respective proteases BACE-1 or γ-secretase, is considered an attractive strategy for preventing disease progression in patients suffering from Alzheimer's Disease." (PMID 22018341, 2011). "BACE1 is a key enzyme involved in the production of amyloid ß-peptide (Aß) in Alzheimer's disease (AD) brains." (PMID 21738672, 2011). "The β-secretase, β-site amyloid precursor protein cleaving enzyme 1 (BACE1), is a prime therapeutic target for lowering cerebral β-amyloid (Aβ) levels in Alzheimer's disease (AD)." (PMID 22204380, 2011). "The expression of miR-9 is altered in brains affected by Alzheimer disease, and BACE1/beta-secretase is a target for translational inhibition by this microRNA." (PMID 20806079, 2010). "The enzyme involved in the production of β-amyloid peptide (Aβ) of Alzheimer's disease, BACE1, functions optimally at lower pH, which led us to investigate a potential role of lactic acid in the processing of amyloid precursor protein (APP)." (PMID 21072203, 2010). "Another target for miR-9 is BACE1/beta-secretase, whose activity is elevated in brains affected by Alzheimer disease." (PMID 20806079, 2010). "BACE1 is a key enzyme in the generation of the Aβ peptide that plays a central role in the pathogenesis of Alzheimer's disease." (PMID 20731874, 2010). "β-Site APP-cleaving enzyme 1 (BACE1) initiates amyloid-β (Aβ) generation and thus represents a prime therapeutic target in treating Alzheimer's disease (AD)." (PMID 20886088, 2010). "For its role in APP processing and Aβ generation, BACE1 is a central actor in the pathogenesis of Alzheimer's disease, and β-secretase inhibition has become a therapeutic goal." (PMID 20041192, 2009). "Beta-secretase (BACE1) is the major enzyme participating in generation of toxic amyloid-beta (Aβ) peptides, identified in amyloid plaques of Alzheimer's disease (AD) brains." (PMID 20721293, 2009). "BACE1, the aspartic protease β-secretase, catalyses the rate-limiting step in the production of amyloid beta, leading to plaque formation in Alzheimer's disease." (PMID 19549314, 2009). "BACE1 has been studied principally for its role in Alzheimer's disease as the β-secretase responsible for generating the amyloid-β protein." (PMID 20041192, 2009). "This retromer complex appears to play a crucial role in the transportation of transmembrane proteins implicated in Alzheimer's disease, such as amyloid precursor protein (APP) and β-site APP cleaving enzyme (BACE1)." (PMID 17903297, 2007). "Here we review BACE1 biology, covering aspects ranging from the initial identification and characterization of this enzyme to recent data detailing the apparent dysregulation of BACE1 in Alzheimer's disease." (PMID 18005427, 2007). "Furthermore, inhibition of lncRNA BC200 increased cell viability and reduced cell apoptosis in an Alzheimer’s disease model by directly targeting BACE1." (PMID 41245147, 2025). "BACE1 cleaves amyloid precursor proteins to generate Aβ which may contribute to Alzheimer's Disease (AD) pathogenesis." (PMID 40587559, 2025). "Furthermore, the lupane triterpenoids isolated from PL can attenuate Alzheimer’s disease by inhibiting beta-site APP cleaving enzyme 1 (BACE1)." (PMID 40709088, 2025). "Furthermore, this study demonstrated that hesperetin supplementation counteracted the upregulation of β-site amyloid precursor protein cleaving enzyme 1 (BACE1), a pathological factor of Alzheimer’s disease (AD) that was induced by metformin." (PMID 40076550, 2025).